DNMT3B (DNA methyltransferase 3 beta)
Diseases named in the same sentence as DNMT3B in open-access papers (continued):
Sharing a sentence is not in itself a finding about the gene and the disease.
liver fibrosis (9 papers, 2015 to 2024). "The Dnmt3b-deficient mice exhibited progression of liver fibrosis upon long-term treatment with TAA, compared to the control mice; these characteristics resembled the pathological features of human liver cirrhosis." (PMID 33277576, 2020). "The liver of the Dnmt3b-deficient mice exhibited an exacerbation of thioacetamide-induced hepatitis, progression of liver fibrosis and a higher incidence of HCC compared with the liver of the control mice." (PMID 33277576, 2020). "To elucidate the cellular role of DNMT3B in the activation of HSCs during the development of liver fibrosis, we observed the morphological changes in HSCs induced by inhibition of DNMT3B with siDNMT3B after TGF-β1 treatment." (PMID 38168140, 2024). "Studies in hepatic stellate cells and liver fibrosis models suggest that MiR-29 upregulates PTEN expression by targeting DNA methyltransferases such as Dnmt1, Dnmt3b, and Set1a to prevent excess liver fibrosis." (PMID 31703360, 2019). "Taken together, these data indicated that the downregulation of PTGIS in liver fibrosis was attributed to DNA methylation and PTGIS gene methylation was mainly caused by DNMT1 and DNMT3b." (PMID 29892223, 2018). "In summary, these findings suggest that targeting HSC reprogramming by attenuation of DNMT3B expression in the tumor environment might represent a promising therapeutic strategy for liver fibrosis and HCC." (PMID 38168140, 2024). "Our results demonstrated that the epigenetic mechanism of miR-29a in the mitigation of liver fibrosis and hepatic inflammation targets DNMT3b and thus hinders ROS production with a decreased expression of proinflammatory cytokines and autophagy in the MCD diet-induced NASH animal model." (PMID 30917489, 2019). "MiR-29b can up-regulate the expression of PTEN via DNMT3b to suppress liver fibrosis." (PMID 30534359, 2018). "Taken together, these data indicated that downregulation of PTGIS in hepatic fibrosis was attributed to hypermethylation of PTGIS promoter which mainly induced by DNMT1 and DNMT3b." (PMID 29892223, 2018). "The HOTAIR acts as a ceRNA to sponge miR-29b and then attenuates DNMT3b, leading to enhancement of PTEN methylation that contributes to liver fibrosis." (PMID 30534359, 2018). "Induction of miR-29b by curcumin to decrease DNMT3B and epigenetically regulate PTEN in hepatic stellate cells was also reported, representing a novel mechanism for the suppression of liver fibrosis." (PMID 26404322, 2015). "In liver fibrosis, RCAN1.4 was decreased by elevated methyltransferases DNMT1 and DNMT3b." (PMID 34707090, 2021).
head and neck squamous cell carcinoma (8 papers, 2008 to 2025). A squamous cell carcinoma that arises from any of the following anatomic sites: lip and oral cavity, nasal cavity, paranasal sinuses, pharynx, larynx, and salivary glands. "The homozygous TT genotype for the DNMT3B rs2424913 had already been previously associated with head and neck squamous cell carcinoma, while the CT genotype was associated with oral lichen planus and with an increase in expression of the protein encoded by this genotype." (PMID 32267380, 2020).
heart failure (8 papers, 2015 to 2025). Inability of the heart to pump blood at an adequate rate to meet tissue metabolic requirements. "And piRNA-6426 alleviates hypoxia-induced cardiomyocyte dysfunction and heart failure in rats by regulating DNMT3B-mediated methylation of SOAT1 promoter, it provides a new direction for the treatment of HF." (PMID 35354120, 2022). "Moreover, DNMT3B also has been implicated as a biomarker in CAD progression to AMI, highlighting its clinical value in heart failure through m5C-mediated regulation." (PMID 40405297, 2025). "Furthermore, the DNA methyltransferase (DNMT) family of proteins, particularly DNMT3A and DNMT3B, plays a pivotal role in heart failure and myocardial fibrosis by regulating gene expression through DNA methylation." (PMID 40290189, 2025). "Moreover, in heart failure patients upregulation of DNMT3a and DNMT3b expression was observed." (PMID 38314203, 2024). "There are data suggesting that DNMT3a and DNMT3b are not operative in heart failure, as DNMT3a/3b ablation in mice did not increase in heart failure after increased cardiac loading from aortic constriction." (PMID 37893188, 2023). "The hypermethylation of CpG islands which was observed in human heart failure might not be due to catalytic activity of Dnmt3a or Dnmt3b in cardiomyocytes." (PMID 26098432, 2015). "Notably, DNMT3a and DNMT3b do not play a role in heart failure." (PMID 40290189, 2025).
neuroblastoma (8 papers, 2016 to 2025). Neuroblastoma (NB) is the most common solid, extracranial childhood tumor. "In ganglioneuroblastoma, the expression of DNMT3B7, which is a truncated isoform of DNMT3B, is higher than in NB patients, and this results in reduced cell growth and induced differentiation." (PMID 33404859, 2021). "In neuroblastoma (NB) cells, genistein treatment led to demethylation of the CDH5 promoter and decreased the expression of DNMT3B." (PMID 41226811, 2025). "miRNA appeared to be downregulated in neuroblastoma cell lines due to promoter methylation, but treatments with 5′azacitidine increased miRNA expression and led to malignancy decrease through downregulation of miRNAs’ targets such as CDK6, DNMT3B, E2F3, OLFM3, and IFNAR1." (PMID 34832966, 2021). "We used 5-aza rather than PCA in the N2a cell lines, as 5-aza has been used regularly in N2a neuroblastoma cell lines, and as we experienced an unintended (and likely compensatory) increase in DNMT3b gene expression level upon treatment with PCA (data not shown)." (PMID 29970123, 2018).
diabetes (7 papers, 2016 to 2025). "In a preliminary analysis, we evaluated variables that might have a potential impact on DNMT1 and DNMT3B expression, including dietary and lifestyle habits, haematological parameters, and cardiovascular or diabetes risk factors." (PMID 27169697, 2016). "In addition to the abnormal expressions of the methyltransferases DNMT3a and DNMT3b mentioned in our previous study, the specific mechanism may be related to vitamin and folic acid deficiency caused by diabetes." (PMID 31781662, 2019). "In addition, in the left ventricular dysfunction of mice caused by diabetes, the expression of DNMT3B could be increased to promote the methylation of the src homology 2 domain-containing transforming protein C1 (p66Shc) promoter and alleviate the cardiac dysfunction." (PMID 35354120, 2022). "Increased expression of Sorbs3 (p = 5.5 × 10–18), Ptpre (p = 0.006) and decreased expression of Pdk4 (p = 0.048) and Dnmt3b (p = 1.2 × 10–11) in VSG GK rats further support the involvement of epigenetic mechanisms in diabetes remission and in the long-term adaptation to bariatric surgery." (PMID 41360887, 2025).
esophageal squamous cell carcinoma (7 papers, 2008 to 2026). Esophageal squamous cell carcinoma (ESCC) is a type of esophageal carcinoma (EC) that can affect any part of the esophagus, but is usually located in the upper or middle third. "Similarly, piR-823 exhibits oncogenic activity in esophageal squamous cell carcinoma (ESCC) by activating aberrant DNA methylation through DNMT3B." (PMID 41596471, 2026). "Recently, a study revealed that piR-823 induced aberrant DNA methylation through the epigenetic pathway DNMT3B and exerted an oncogenic role in esophageal squamous cell carcinoma (ESCC)." (PMID 35637965, 2022). "In esophageal squamous cell carcinoma (ESCC) tissues, upregulated piR-823 may play a tumorigenic role by inducing abnormal DNA methylation of DNMT3B through epigenetic inheritance." (PMID 34118972, 2021).
liver cancer (7 papers, 2013 to 2024). An epithelial or non-epithelial malignant neoplasm that arises from the liver. "Both TCGA database and Human Protein Atlas program database showed that compared to the normal liver tissues, the mRNA and protein levels of DNMT3B in liver cancer tissues were much higher." (PMID 33522955, 2021). "The expression of DNMT3b/OCT4 may confer sorafenib resistance in HCC, and the DNMT3b inhibitor exhibited a synergistic effect with sorafenib on sorafenib-resistant liver cancer." (PMID 31771617, 2019). "In liver cancer cells, TGF-β1 can regulate CD133 expression through the inhibition of DNMT1 and DNMT3b expressions; TGF-β1 stimulation results in a significant demethylation of CD133 promoter-1." (PMID 23560091, 2013).
non-small cell lung carcinoma (7 papers, 2008 to 2022). A group of at least three distinct histological types of lung cancer, including non-small cell squamous cell carcinoma, adenocarcinoma, and large cell carcinoma. "In non-small-cell lung cancer (NSCLC), MYC recruits DNMT3B to the promoter of the tumor suppressor, Ras Association Domain-containing Protein 1 (RASSF1A), silencing its expression through DNA hypermethylation." (PMID 28505071, 2017). "UHRF1 was also shown to be overexpressed in primary non-small cell lung cancer (NSCLC) and its high expression level was associated with an increase in the expression of DNMT1, DNMT3A, and DNMT3B and correlated with hypermethylation of p16INK4A promoter." (PMID 27839516, 2016). "In this study, we measured the mRNA expression levels of three methylation-regulating genes (DNMT1, DNMT3b, and MBD2) in 148 tumour samples from patients with non-small cell lung cancer (NSCLC) using quantitative real-time polymerase chain reaction and then determined their prognostic values." (PMID 18414412, 2008).
pulmonary fibrosis (7 papers, 2018 to 2025). Chronic progressive interstitial lung disorder characterized by the replacement of the lung tissue by connective tissue, leading to progressive dyspnea, respiratory failure, or right heart failure. "Consistently, DNMT3B deficiency in myeloid cells exacerbates pulmonary fibrosis, suggesting a protective role for DNMT3B in IPF via the regulation of macrophage polarization." (PMID 37681924, 2023). "Collectively, myeloid cell specific DNMT3B deficiency exacerbates the development of pulmonary fibrosis induced by bleomycin potentially by regulating alternative macrophage polarization." (PMID 35725453, 2022). "To test this assumption, we assessed macrophage subpopulations and fibrotic responses in the lungs of myeloid cell specific Dnmt3b deficient mice during bleomycin-induced pulmonary fibrosis." (PMID 35725453, 2022). "The increased alternative macrophage polarization in myeloid DNMT3B deficient mice was accompanied by increased pulmonary fibrosis which suggests that macrophage DNMT3B inhibits the development of pulmonary fibrosis by restricting alternative macrophage polarization." (PMID 35725453, 2022). "In order to determine the role of DNA methylation in macrophages during pulmonary fibrosis, we subjected macrophage specific DNA methyltransferase (DNMT)3B, which mediates the de novo DNA methylation, deficient mice to the bleomycin-induced pulmonary fibrosis model." (PMID 35725453, 2022). "This increased M2 polarization in myeloid DNMT3B-deficient mice was accompanied by increased pulmonary fibrosis, which suggests that macrophage DNMT3B inhibits the development of pulmonary fibrosis by restricting alternative macrophage polarization." (PMID 40358164, 2025). "In summary, these data suggest that myeloid DNMT3B represses fibrotic macrophage polarization and protects against bleomycin induced pulmonary fibrosis." (PMID 35725453, 2022). "The results demonstrate that myeloid DNMT3B limits the development of pulmonary fibrosis by limiting M2 macrophage polarization potentially by methylation of the promoter of the gene encoding arginase 1 (Arg1)." (PMID 35725453, 2022). "Overall, the present study demonstrates that myeloid DNMT3B represses fibrotic macrophage polarization and ameliorates the development of bleomycin induced pulmonary fibrosis." (PMID 35725453, 2022). "Given the importance of macrophages in the development of pulmonary fibrosis and the role of DNMT3B in macrophage polarization, myeloid DNMT3B limits the development of pulmonary fibrosis by limiting M2 macrophage polarization potentially by methylation of the promoter of the gene encoding Arg1." (PMID 40358164, 2025). "Interestingly, inhibition of DNA methylase levels (DNMT1, DNMT3a, and DNMT3b) promotes PPARγ expression and improves pulmonary fibrosis." (PMID 37986543, 2024). "We show that DNMT3B deficiency promotes alternative macrophage polarization induced by IL4 and TGFB1 in vitro and also enhances profibrotic macrophage polarization in the alveolar space during pulmonary fibrosis in vivo." (PMID 35725453, 2022). "To determine the potential role of DNMT3B in macrophage polarization during pulmonary fibrosis in vivo, we subjected myeloid cell specific DNMT3B deficient mice (Dnmt3bfl/flLysMCre mice) and their littermate controls (Dnmt3bfl/fl mice) to the bleomycin-induced lung fibrosis model." (PMID 35725453, 2022). "Here we show that the loss of DNMT3B in macrophages promotes alternative, but not classic, macrophage polarization, and is associated with enhanced bleomycin-induced pulmonary fibrosis." (PMID 35725453, 2022). "Moreover, myeloid specific deletion of DNMT3B promoted the development of experimental pulmonary fibrosis." (PMID 35725453, 2022). "Alternatively activated macrophages have been suggested to promote the development of bleomycin induced fibrosis and therefore the effect of DNMT3B on macrophage polarization may affect the development of pulmonary fibrosis." (PMID 35725453, 2022).
pulmonary fibrosis (continued). "Then, using a myeloid cell-specific DNMT3B deficient mice, they demonstrated in the bleomycin-induced pulmonary fibrosis model that the lack of DNMT3B increased the recruitment of fibrotic AMs (SiglecFlowCD11bhi) as compared to classic alveolar macrophage population (SiglecFhiCD11blow)." (PMID 37681924, 2023). "Therefore, given the importance of macrophages in the development of pulmonary fibrosis and the role of DNMT3B in macrophage polarization, we hypothesized that macrophage specific DNMT3B may play a role in fibrosis development." (PMID 35725453, 2022).
endometrial cancer (6 papers, 2010 to 2023). Primary or metastatic malignant neoplasm involving the endometrium (mucous membrane that lines the endometrial cavity). "It has been suggested that overexpression of DNMT3a and DNMT3b contribute to hypermethylation of ERα and PR, subsequently silencing these genes in endometrial cancer." (PMID 35372016, 2022). "In this study, we demonstrated that TCF3 is epigenetically silenced by EZH2 and DNMT3B and functions as a tumor suppressor in endometrial cancer." (PMID 34175897, 2021).
Insulin resistance (6 papers, 2016 to 2026). Increased resistance towards insulin, that is, diminished effectiveness of insulin in reducing blood glucose levels. "Through epigenetic mechanisms, the elevated saturated fatty acids resulted in increased DNMT3b bound to the promoter region of PPARγ1, which may contribute to deregulated adipose tissue macrophage polarization and ultimately cause inflammation and insulin resistance." (PMID 30917489, 2019). "In another study, DNMT3b downregulation in ATMs was found to promote an anti-inflammatory state and enhanced insulin sensitivity, revealing the contribution of DNMT3b-mediated methylation at the Pparg promoter to increased inflammatory conditions and insulin resistance." (PMID 34638914, 2021). "However, male D3bKO mice have no change in body weight but exhibit insulin resistance, suggesting a sexual dimorphism of metabolism in the brown fat Dnmt3b knockout model." (PMID 34947856, 2021).
lung adenocarcinoma (6 papers, 2016 to 2026). A carcinoma that arises from the lung and is characterized by the presence of malignant glandular epithelial cells. "HOXB3 increases the expression of DNA methyltransferase (DNMT3B), which is in turn recruited to the RASSF1A promoter, resulting in hypermethylation and silencing of RASSF1A expression in lung adenocarcinoma." (PMID 29439669, 2018).
osteoarthritis (6 papers, 2020 to 2025). A noninflammatory degenerative joint disease occurring chiefly in older persons, characterized by degeneration of the articular cartilage, hypertrophy of bone at the margins and changes in the synovial membrane. "The pathogenic role of DNMT3B was confirmed in a chondrocyte-specific knockout mouse model, which also developed osteoarthritis." (PMID 39819598, 2025). "Additionally, downregulation of mi-RNA-29b is promoted via Dnmt3b, and its overexpression is found to prevent osteoarthritis through the Dnmt3b/mi-RNA-29b/PTHLH/CDK4/RUNX2 axis, thus suppressing chondrocyte apoptosis and extracellular matrix degradation." (PMID 34440172, 2021). "The absence of Dnmt3b from chondrocytes induces osteoarthritis." (PMID 39819598, 2025).